COMT (catechol-O-methyltransferase)
Diseases named in the same sentence as COMT in open-access papers (continued):
Sharing a sentence is not in itself a finding about the gene and the disease.
preeclampsia (continued). "The results reported herein have significant implications not only for research in preeclampsia, but also for future studies investigating genetic variation in the COMT gene." (PMID 21304959, 2011). "We also found that epistasis between fetal COMT and MTHFR, which is associated with decreased enzyme activity as well, was associated with significantly increased risk for preeclampsia in this population." (PMID 21304959, 2011). "MHM, the process responsible for supplying COMT with the methyl group necessary for 2-ME synthesis, could be compensatorily activated in preeclampsia to supply methyl groups enough to sustain adequate concentration of 2-ME." (PMID 40123939, 2025). "Elevated homocysteine levels might be associated with an increased risk of preeclampsia, and homocysteine is converted into S-adenosyl homocysteine (SAH), a potent COMT inhibitor." (PMID 26000015, 2015). "Logistic regression model of COMT-MTHFR interaction risks for preeclampsia." (PMID 21304959, 2011). "Ethnic variation in each gene raises the possibility that different alleles of COMT and MTHFR could contribute to preeclampsia risk in different racial groups." (PMID 21304959, 2011). "With COMT being responsible for methylating 2-Hydroxyestradiol (2-HE) into 2-ME, it has been demonstrated that low activity or expression of this enzyme could be involved in the pathogenesis of preeclampsia." (PMID 40123939, 2025). "While we can conclude that BMI was not driving the relationship between COMT and the risk for preeclampsia in the present study, it is not valid to extend these results past the current sample since individuals with preeclampsia are oversampled in a case-control study." (PMID 21304959, 2011). "Finally, we assessed whether the relationship between COMT and preeclampsia was influenced by MTHFR." (PMID 21304959, 2011). "COMT haplotype analysis for mothers and fetuses with and without preeclampsia." (PMID 21304959, 2011). "The more significant nonrandom distribution of women with preeclampsia with a maternal protective ACCG COMT allele suggests that when the fetus is at high risk, it is preferred to have a maternal protective ACCG COMT allele to potentially offset the risk to some degree." (PMID 21304959, 2011).
post-traumatic stress disorder (14 papers, 2011 to 2025). An anxiety disorder precipitated by an experience of intense fear or horror while exposed to a traumatic (especially life-threatening) event. "The COMT Val158Met polymorphism has been implicated in human mental illness, with Met/Met homozygotes associated with increased susceptibility to posttraumatic stress disorder (PTSD)." (PMID 23596403, 2013). "Notably, COMT (rs4680) affects both skeletal muscle metabolism during exercise and forebrain function during cognitive tasks, indicating associations with stress resilience or even post-traumatic stress disorder." (PMID 39766802, 2024). "Further analyses revealed that this patient subset had high rates of post-traumatic stress disorder (PTSD), and enrichment in several distinct genetic polymorphisms associated with cellular responses to stress and DNA damage (PARP1), and in striatal dopamine processing (ANKK1, COMT, DRD2)." (PMID 28257413, 2017).
Alzheimer disease (13 papers, 2009 to 2025). A progressive, neurodegenerative disease characterized by loss of function and death of nerve cells in several areas of the brain leading to loss of cognitive function such as memory and language. "The aim of this study was to investigate the possible association of levels of BDNF and COMT gene expression and methylation in peripheral blood cells with the development of Alzheimer’s disease (AD)." (PMID 36830773, 2023). "The aim of this study is to examine the influence of the catechol-O-methyltranferase (COMT) gene (polymorphism Val158 Met) as a risk factor for Alzheimer's disease (AD) and mild cognitive impairment of amnesic type (MCI), and its synergistic effect with the apolipoprotein E gene (APOE)." (PMID 19793392, 2009). "Using fMRI, the pharmacological effect of cholinesterase inhibitors for Alzheimer’s disease (AD), or that of a peripheral inhibitor of the enzyme catechol-O-methyltransferase for PD, have been studied and detected as significant changes of BOLD signal in comparison with placebo." (PMID 35562711, 2022).
diabetes (12 papers, 2006 to 2025). "The amount of available data on the association between diabetes and polymorphisms in the “pain genes” (COMT and OPRM1) is very limited." (PMID 40649008, 2025). "Diabetes, substance, polymorphisms of COMT rs6269 (AA vs. AG vs. GG), and their interaction explained R2 = 2.5%, p < 0.001 of the variance in the dose of analgesics." (PMID 40649008, 2025). "Diabetes, substance, polymorphisms of COMT rs4633 (CC vs. CT vs. TT), and their interaction explained R2 = 3.0%, p = 0.001 of the variance in the dose of analgesics." (PMID 40649008, 2025). "Diabetes, substance, polymorphisms of COMT rs4818 (CC vs. CG vs. GG), and their interaction explained less than R2 = 2.3%, p < 0.001 of the variance in the dose of analgesics." (PMID 40649008, 2025). "In conclusion, both diabetes and genetic polymorphisms in the COMT and OPRM1 genes play an important role in postoperative opioid demand and pain perception." (PMID 40649008, 2025). "Diabetes, substance, polymorphisms of COMT rs4680 (AA vs. AG vs. GG), and their interaction explained R2 = 3.3%, p = 0.001 of the variance in the dose of analgesics." (PMID 40649008, 2025). "Two-way interactions between diabetes and COMT polymorphisms rs4633, rs4680, and rs6269 further influenced the analgesic requirements." (PMID 40649008, 2025). "The only significant effect was a two-way interaction between diabetes and GG vs. AA polymorphisms in COMT rs4680." (PMID 40649008, 2025). "We also found a significant two-way interaction between diabetes and (CT vs. CC) polymorphisms in COMT rs4633." (PMID 40649008, 2025). "Among the diabetes-associated plasma proteins, only those encoded by COMT and DCXR showed a potential causal effect with T2DM complications (p < 0.05)." (PMID 39280009, 2024). "Association of the COMT gene with diabetes and nephropathy has been reported in a study conducted on an Asian Indian population in which a genetic variant showed an association with diabetic nephropathy." (PMID 30011860, 2018). "First of all, genetic variances of COMT associated with less enzymatic activity would be prone for the onset of diabetes, metabolic syndrome, and liver damage with certain metabolic insults associated with COMT suppression." (PMID 28801594, 2017). "Additionally, we found a significant two-way interaction between diabetes and AG vs. AA polymorphisms in COMT rs4680." (PMID 40649008, 2025). "At the same time, the effect of GG vs. AA COMT rs6269 polymorphisms was significant for the patients with diabetes, β = −0.24, Post SD = 0.11, 95% CI [−0.46, −0.03], p < 0.001, but not for those without diabetes, β = 0.07, Post SD = 0.05, 95% CI [−0.02, 0.17], p = 0.140." (PMID 40649008, 2025). "We further decomposed the two-way interaction by examining the differences between patients with CC vs. CT vs. TT alleles in the COMT rs4633 gene separately for patients with and without diabetes." (PMID 40649008, 2025). "We found that, in patients without diabetes, the effect of the AG vs. AA COMT rs4680 polymorphisms was not significant, β = −0.01, Post SD = 0.04, 95% CI [−0.07, 0.07], p = 0.820." (PMID 40649008, 2025). "We further decomposed the two-way interaction by investigating the differences between patients with AA vs. AG vs. GG alleles in the COMT rs6269 gene separately for patients with and without diabetes." (PMID 40649008, 2025). "We further decomposed the two-way interaction by investigating the differences between patients with AA vs. AG vs. GG alleles in the COMT rs4680 gene separately for patients with and without diabetes." (PMID 40649008, 2025). "An analysis of another COMT rs6269 polymorphism revealed that patients with AA and GA alleles with or without diabetes received similar doses of analgesics." (PMID 40649008, 2025). "We found that, in patients without diabetes, the effect of the CT vs. TT COMT rs4633 polymorphisms was not significant, β = −0.01, Post SD = 0.04, 95% CI [−0.08, 0.07], p = 0.780." (PMID 40649008, 2025).
diabetes (continued). "The three-way interaction between diabetes, polymorphisms in COMT rs4633, and type of substance was not significant, suggesting that the interaction between diabetes and COMT rs4633 polymorphisms was similarly associated with morphine, ketoprofen, and acetaminophen use." (PMID 40649008, 2025). "The three-way interaction between diabetes, polymorphisms in COMT rs4680, and the type of substance was not significant, indicating that the interplay between diabetes and COMT rs4680 polymorphisms was associated similarly with doses of morphine, ketoprofen, and acetaminophen." (PMID 40649008, 2025). "Furthermore, factors such as sex, age and diagnosed or (treated) diabetes did not influence the differences in the pain threshold and pain tolerance in patients with different variants of the COMT and OPRM1 genes." (PMID 36292660, 2022). "The aim of the present study was to investigate a possible association of the COMT and OPRM1 genotypes with pain perception in patients undergoing total hip replacement (THR) and total knee replacement (TKR), taking into account aspects such as age, sex and diabetes." (PMID 36292660, 2022). "The aim of the study was to investigate a possible association of the catechol-O-methyltransferase (COMT) and μ-opioid receptor (OPRM1) genotypes with pain perception in patients undergoing total hip replacement and total knee replacement taking into account aspects such as age, sex and diabetes." (PMID 36292660, 2022). "Of the top 15 proteins found by Cytoscape 3.6.1, 8, CAT and OGG1 (downregulated) and CASP3, COMT, CYP1B1, DPYD, NQO1, and PTGS1 (upregulated), were dysregulated in diabetes-related kidney disease." (PMID 34367469, 2021). "The frequency of COMT low activity genotype was higher among the subjects with abnormal RBS and diabetes." (PMID 30011860, 2018). "We found insignificant effects of COMT rs4680, rs4633, rs6269, and rs4818 in patients without diabetes." (PMID 40649008, 2025). "Furthermore, the COMT genotyping was performed in a random sample of individuals drawn from a genetically homogenous white Norwegian population and being unselected except from the fact that they did not have diabetes." (PMID 17577421, 2007).
hyperhomocysteinemia (12 papers, 2007 to 2023). A serious metabolic condition caused by mutations in the MTHFR gene, medications, or nutritional deficiency. "For example, hyperhomocysteinemia is an important risk factor for a variety of conditions associated with low COMT activity, including neurodegenerative disorders, cardiovascular disease, and hormonal cancers." (PMID 19365560, 2009). "Therefore, the current study suggests that COMT inhibitors can not only involve in the secure delivery of L-dopa but reduce potential side effects such as hyperhomocysteinemia caused by L-dopa intervention." (PMID 36839259, 2023). "Specifically, mutations in the MTHFR gene can increase the incidence of hyperhomocysteinemia, which could be ameliorated by the addition of COMT inhibitors to therapy, presenting a possibility for clinical interventions based on pharmacogenomic testing." (PMID 34281267, 2021). "Moreover, this meta-analysis elucidated that COMT inhibitors might be beneficial in ameliorating hyperhomocysteinemia and folate deficiency induced by the L-dopa treatment." (PMID 36839259, 2023). "L-DOPA methylation generates homocysteine by the action of catechol-O-methyltransferase (COMT), and hyperhomocysteinemia might contribute to the loss of therapeutic effect of L-DOPA over time due to the negative allosteric properties of homocysteine on D2 receptors." (PMID 33202534, 2020). "A meta-analysis of the homocysteine levels in L-DOPA-treated idiopathic Parkinson’s disease has reported that COMT inhibitors counteract hyperhomocysteinemia." (PMID 33202534, 2020). "Results from previous studies that assessed the effect of COMT inhibitors on levodopa-induced hyperhomocysteinemia are conflicting." (PMID 27493964, 2016). "Hyperhomocysteinemia has been attributed to levodopa: its O-methylation by catechol-O-methyltransferase (COMT) can provide a substrate for homocysteine synthesis." (PMID 19941660, 2009). "Thus, the current data suggest that the COMT inhibitor reduces the side effects of L-dopa related to hyperhomocysteinemia." (PMID 36839259, 2023). "Future studies are needed to determine whether inhibition of homocysteine synthesis using clinically available COMT inhibitor can protect NPCs against levodopa-induced hyperhomocysteinemia." (PMID 23209759, 2012). "Furthermore, the results did not support the finding that COMT inhibitors have a preventive effect on hyperhomocysteinemia, which may be associated with levodopa therapy." (PMID 27493964, 2016). "Our results showed that levodopa treatment may cause a slight increase in the Hcy levels in PD compared with dopamine agonists and that COMT inhibitors may not have a significant effect on preventing hyperhomocysteinemia." (PMID 27493964, 2016). "The hyperhomocysteinemia in Levodopa treated PD patients could be related with the increased consumption of SAM in the O-methylation of Levodopa, catalyzed by catechol-O-methyltransferase (COMT)." (PMID 20027219, 2009). "A unifying hypothesis that hyperhomocysteinemia may exert its pathogenic effects largely through metabolic accumulation of SAH, a potent non-competitive inhibitor of COMT-mediated methylation metabolism of various catechol substrates was recently proposed." (PMID 17264883, 2007).
mood disorder (12 papers, 2012 to 2025). A cognitive disorder a disturbance in which the person's mood is hypothesized to be the main underlying feature. "Though in our sample too few patients were taking COMT inhibitors to draw definitive conclusions, functional polymorphisms in COMT have been associated with motivational and mood disorders." (PMID 37425947, 2023). "Women with the Met variant in COMT gene may exhibit higher catecholamine accumulation, increasing their risk for mood disorders and oxidative stress." (PMID 39642577, 2024). "The association between COMT Val158Met and mood disorders has been pointed out in the literature." (PMID 30991630, 2019). "Reduced COMT activity can exacerbate stress-related symptoms and hormonal imbalances, contributing to mood disorders and cortisol dysregulation." (PMID 39642577, 2024). "The review highlights the impact of COMT rs4680 on stress response and mood disorders, FUT2 rs602662 and rs601338 on vitamin B12 absorption and cortisol metabolism, and MTHFR rs1801133 and rs1801131 on homocysteine levels and cardiovascular risk." (PMID 39642577, 2024). "This measure might elucidate what kind of dopaminergic transmission, determined by COMT, is responsible for the pathogenesis of mood disorders in the obese population." (PMID 30991630, 2019). "The COMT met/met genotype has, however, been shown to interact with maternity stressors in postpartum depression and with stressors within the year preceding the onset of the first mood disorder episode in depressive adults." (PMID 22745815, 2012).
prostate carcinoma (11 papers, 2010 to 2024). A carcinoma that arises from epithelial cells of the prostate gland. "The AA genotype and the A allele of rs4680 (COMT) appeared to be inversely associated with the risk of prostate cancer in adjusted models for both Afro-Caribbean and native African men." (PMID 27074016, 2016). "The association of the COMT (rs4680) polymorphism with the risk of prostate cancer has been investigated only in Caucasian and Asian populations, and three meta-analyses have reported no overall association." (PMID 27074016, 2016). "In summary, our results suggest that some polymorphisms of genes involved in estrogen metabolism, particularly COMT, are associated with prostate cancer risk in men of African ancestry." (PMID 27074016, 2016). "By contrast, the homozygous AA genotype of rs4680 (COMT) appeared to be inversely associated with prostate cancer risk in adjusted models, for both Afro-Caribbean (OR: 0.53; 95% CI: 0.32–0.88; Ptrend: 0.04) and native African (OR: 0.26, 95% CI: 0.08–0.83; Ptrend: 0.003) populations." (PMID 27074016, 2016). "COMT plays a role in both colorectal-, gastric- and prostate cancer, but has also been published in relation to many other neoplasms." (PMID 39543761, 2024). "In prostate cancer, COMT expression can inhibit the migration ability of tumor cells and increase the occurrence of cell apoptosis." (PMID 38352696, 2024). "Levels of COMT protein were also lower in prostate cancer compared to BPH as determined by immunohistochemical analysis of clinical specimens (p = 0.004)." (PMID 34587154, 2021). "Both the Cancer Genome Atlas (TCGA) and immunohistochemical analysis of clinical specimens demonstrated a reduction of COMT expression in prostate cancer." (PMID 34587154, 2021). "Our results are the first to show that the COMT gene plays a protective role in prostate cancer through the apoptosis pathway and that COMT is regulated by miRNA." (PMID 34587154, 2021). "Databases identified several miRNAs capable of binding COMT and of these, miR-195 was observed to be increased in prostate cancer according to TCGA." (PMID 34587154, 2021). "In this report, we characterized the functional role and regulation of the COMT gene in prostate cancer cells." (PMID 34587154, 2021). "This property is supported by the lower levels of COMT observed in prostate cancer compared to normal regions according to TCGA though a trend (p = 0.2) but significantly compared to BPH in our clinical specimens (p = 0.004)." (PMID 34587154, 2021). "In summary, our results are the first to show the COMT gene to trigger cell death in prostate cancer by enhancing apoptosis through its pathway genes." (PMID 34587154, 2021). "Finally, cotreatment with epigallocatechin gallate (EGCG) inhibited catechol-O-methyltransferase (COMT) activity, decreasing COMT protein content and thereby arresting the cell cycle of PC-3 human prostate cancer cells." (PMID 38474512, 2024). "We conclude that COMT plays a protective role in prostate cancer cells and thus, could be a potential gene of interest for therapeutic development for this cancer as well as a possible biomarker." (PMID 34587154, 2021). "In this study, we determined the functional effects and regulation of COMT in prostate cancer." (PMID 34587154, 2021). "As COMT expression is low in prostate cancer, its regulation was determined." (PMID 34587154, 2021). "It is thus apparent that these genes mediate COMT effects on apoptosis in prostate cancer cells." (PMID 34587154, 2021). "Also, western analyses of prostate cancer cell lines show COMT levels to be minimal in DuPro and DU145 and thus, these cells were used for further analyses." (PMID 34587154, 2021). "COMT may thus be a potential biomarker and gene of interest for therapeutic development for prostate cancer." (PMID 34587154, 2021).